APOA1 (apolipoprotein A1)
Diseases named in the same sentence as APOA1 in open-access papers (continued):
Sharing a sentence is not in itself a finding about the gene and the disease.
breast carcinoma (continued). "Therefore, in this study, we utilized adenovirus carrying ApoA1 to construct a replicative oncolytic adenovirus (ADV-ApoA1) for breast cancer treatment." (PMID 38566092, 2024). "Similarly, in mouse models of breast cancer, ApoA1 demonstrated its ability to suppress metastasis of breast cancer." (PMID 38566092, 2024). "Building upon these discoveries, we developed an oncolytic adenovirus encoding ApoA1 and assessed its efficacy in suppressing TNBC growth and metastasis across diverse mouse models, including orthotopic breast cancer, spontaneous breast cancer, and human xenograft transplants." (PMID 38566092, 2024). "Another study revealed that an increase in the APOB to APOA1 ratio is associated with an increase in the severity of breast cancer, but this was not statistically significant." (PMID 38067270, 2023). "Lower serum ApoA1 levels even had a practical function to predict the recurrence of breast cancer." (PMID 35100989, 2022). "Therefore, our study provides a feasible strategy to boost the therapeutic effect of breast cancer therapy by using the ApoA1-lipsome drug-delivery system." (PMID 33652957, 2021). "Studies have reported that Apos are strongly correlated with the development of cancer, for example, breast cancer patients with OM may have lower levels of ApoA1 compared with NOM patients." (PMID 32090248, 2020). "For APOA1, it is one of the most significant genes correlated with the proteomic profile that are closely related to breast cancer and may be involved in robust detection of disease progression." (PMID 29179495, 2017). "Besides, in breast cancer, the expression level of ApoA1 increased in patients who showed good response to preoperative chemotherapy, which demonstrated that higher ApoA1 increased chemo-sensitivity." (PMID 26646794, 2016). "It is at this stage unknown how much apoA1 in circulation is contributed by the mammary tissue, but the retention of apoA1 in breast cancer tissues is in accordance with the observation of lower plasma HDL/apoA1 in breast cancer patients." (PMID 23829168, 2013). "Supportively, apoA1 was also identified in the breast cancer tissues and ex vivo cultured medium." (PMID 23829168, 2013). "Therefore we tested the contribution of APOA1 rs670 to breast cancer in recruited patients cross-sectionally at baseline and longitudinally at follow-up." (PMID 23829168, 2013). "However, the contribution of SNPs on the APOA1/C3/A5 gene cluster to breast cancer is yet to be defined." (PMID 23829168, 2013). "Furthermore, a successful reduction of breast cancer growth in mice by vitamin D treatment was accompanied by decrease of apoA1 production in tumor tissues." (PMID 23829168, 2013). "The risk of mortality in lymph node-negative APOA1 rs670 A/A carrying breast cancer patients was also higher than APOA1 rs670 G/G counterparts (HR=9.87, 95% CI=1.60-60.81, p=0.014)." (PMID 23829168, 2013). "Down-regulation of ApoA1 is a consistent finding in serum or tissue in the setting of several types of cancer, and our study validated this phenomenon in the serum of breast cancer patients." (PMID 19400944, 2009). "Therefore, the altered HDL/apoA1 levels observed in APOA1 rs670 A carriers may participate in the tumorigenesis, survival, ER/PR status of breast cancer cells." (PMID 23829168, 2013). "The patients exhibited significantly lower levels of key apolipoproteins, including apoA-1, apoA-2, apoC-2, and apoC-4, compared to luminal A, luminal B, and HER2-positive breast cancer patients (p-values ranging from 0.004 to 0.057)." (PMID 40430118, 2025). "According to the xiantao database, COL1A2, COL3A1, FGA, LUM, APOA1, APOH, and COL5A2 were more highly expressed in breast cancer than in normal tissues (p < 0.05), while the opposite pattern was seen for ALB and FBN1 (p < 0.05)." (PMID 37079213, 2023).
breast carcinoma (continued). "In contrast, the linkage among APOA1 rs670, APOC3 rs2854116 and APOC3 rs2854117 was lost in breast cancer patients, while significant linkage was only observed between the two APOA5 SNPs (D’=1.00)." (PMID 23829168, 2013). "The distributions of the tested SNPs (APOA1 rs670, APOC3 rs2854116, APOC3 rs2854117, APOA5 rs662799 and APOA5 rs2075291) fitted the Hardy-Weinberg equilibrium in both breast cancer patients and healthy controls." (PMID 23829168, 2013). "As plasma apoA1 level is regulated by estrogen and thus TAM treatments, the timing of plasma apoA1 measurement in breast cancer patients is critical." (PMID 23829168, 2013). "Notably, abnormalities in TC, LDL-C, HDL-C, and ApoA1 are more prevalent in the TNBC and human epidermal growth factor receptor 2 (HER2)-positive breast cancer subtypes compared to the luminal subtype." (PMID 40666099, 2025). "APOA1 was also upregulated under Tamoxifen treatment, but no prognostic value in breast cancer has been found yet." (PMID 38233507, 2024). "We further examined the prognostic values of the mRNA expressions of APOA1, APOC3, APOA4, and APOA5 by using two online survival analysis software packages that were established through analyses of predominantly Western patients with breast cancer." (PMID 34226567, 2021). "Clinically, our finding of worst outcome in APOA1 rs670 A/A breast cancer patients as compared to their non-A/A counterparts provides pivotal implications in personalized treatment regimen and therapeutic strategies." (PMID 23829168, 2013). "Though the effects of these SNPs on APOA1/C3/A5 on metabolic disorders have been widely studied and reviewed, their contributions to breast cancer have not been determined in detail." (PMID 23829168, 2013). "On the other hand, due to the low plasma HDL-C and tumor ER/PR negativity in the APOA1 rs670 A/A carriers, the usage of TAM in these breast cancer patients may be controversial and require further evaluation." (PMID 23829168, 2013). "In a placebo-controlled study involving 147 postmenopausal women with early breast cancer, exemestane had no major effect on the lipid profile except for a modest but significant decrease from baseline in HDL cholesterol (P < 0.001) and apolipoprotein A1." (PMID 19531217, 2009). "However, there is evidence that inulin supplementation does not change cholesterol and triacylglycerols in women without cancer and with breast cancer during chemotherapy with cyclophosphamide and doxorubicin; instead, HDL-c and apolipoprotein A1 could be reduced." (PMID 31772611, 2019).
amyloidosis (72 papers, 2011 to 2026). A disorder characterized by the localized or diffuse accumulation of amyloid protein in various anatomic sites. "Here, we report a patient with cardiac ApoA-I amyloidosis who carried a homozygous variant of p.Leu202Arg in APOA1." (PMID 39152105, 2024). "Genetically, ApoA-I amyloidosis is caused by amyloidogenic variants of APOA1 inherited in an autosomal dominant fashion." (PMID 39152105, 2024). "Among the human amyloidosis identified so far, a hereditary systemic amyloidosis is caused by mutations in the gene encoding Apolipoprotein A1 (ApoA-I), the major protein in high-density lipoproteins." (PMID 35408859, 2022). "The causes of this phenomenon can be explained by amyloidosis and other translational and posttranslational modifications of apolipoprotein A-1 (apoA-1)." (PMID 32178676, 2020). "Thus, four variants in APOA1 identified in 42 individuals (0.41% of the population) have either previously been associated with or suspected of causing amyloidosis." (PMID 23209431, 2012). "We have identified a significant increase of SNCA, TTR, APOA1, and light chain variable of immunoglobulin protein, the proteins whose aggregation leads to different types of amyloidosis." (PMID 41379876, 2025). "ApoAI and ApoAIV amyloidosis belong to rare amyloidosis types and contain APOA1 and APOA4 as amyloidogenic proteins, respectively." (PMID 40701201, 2025). "Other rare types of amyloidosis such as ApoA1 amyloidosis, AH, AHL, AA and AANF have treatment options that include organ transplantation and treating individual etiologies." (PMID 38682372, 2024). "Several subtypes of amyloidosis exist, such as light-chain amyloidosis, serum amyloid A protein, transthyretin (TTR) amyloidosis, beta-2 microglobulin amyloidosis, and apolipoprotein A1 or A2 amyloidosis." (PMID 39791066, 2024). "For the patient in this study, the clinical picture and results of biochemical analysis were compatible with those of ApoA-I amyloidosis; however, the patient unexpectedly harbored a homozygous pathogenic variant, p.Leu202Arg, in the APOA1 gene." (PMID 39152105, 2024). "As an example, the identification of apolipoprotein A1 in the amyloid composition of both patients is a potential prerequisite for the diagnosis of another type of amyloidosis." (PMID 37833900, 2023). "A lot of naturally occurring ApoA1 variants have so far been identified, impacting levels of HDL and amyloidosis of the protein." (PMID 32456156, 2020). "Subnetwork 2 showed potential functional relationships between proteins FGB, FGA, APOA1, and afibrinogenemia congenital, amyloidosis familial visceral, and hypoalphalipoproteinemia." (PMID 30532734, 2018). "Population-based resequencing of APOA1 identified a majority of rare NS variants associated with reduced apoA-1 and HDL cholesterol levels and/or predisposing to amyloidosis." (PMID 23209431, 2012). "In conclusion, population-based resequencing of APOA1 identified a majority of rare NS variants associated with reduced apoA-I and HDL cholesterol levels and/or predisposing to amyloidosis." (PMID 23209431, 2012). "In addition to neurogenesis, cell adhesion/inflammation, and synaptic signaling, cholesterol metabolism, and especially lipoproteins (APOA1, APOC1, APOC3, APOF), were associated with depressive symptoms when amyloid pathology was present." (PMID 41451799, 2025). "Moreover, if the content of lysozyme and apolipoprotein A1 in the amyloid composition is comparable, the quantitative criterion in diagnosing the type of amyloidosis will lose its reliability." (PMID 37833900, 2023). "INS, IL6 increases while APOE and APOA1 decrease the prediction of amyloidosis." (PMID 32753925, 2020). "ApoA1-induced amyloidosis often trigger asymptomatic hepatopathy and nephropathy." (PMID 32456156, 2020). "These ApoA1 variants have undeniable interest because they may affect lecithin-cholesterol acyltransferase (LCAT) activity and promote the formation of amyloidosis." (PMID 32456156, 2020).
amyloidosis (continued). "Therefore, studying the effect of ApoA1 on vascular integrity and amyloid clearance may provide new therapeutic options for CAA." (PMID 41516203, 2025). "In the SMC-calc vs. SMC comparison based on limma, clusters related to high-density lipoprotein (HDL) assembly (PF4V1, APOA1, LPXN, AFP, A2M, and MMP1) and amyloidosis (CX3CL1, APOE, PLIN3, TGFBI, and CH25H) were identified." (PMID 41301179, 2025). "The combination is generally not seen in other types of amyloidosis except rare hereditary apolipoprotein A1 amyloidosis." (PMID 29651545, 2018). "The expression levels of Apoa1 and Apoa2 mRNA did not change after CR treatment and amyloidosis induction." (PMID 28225824, 2017). "Besides this hereditary form, ApoA1 amyloidosis can be found as a non-hereditary form, characterized by the wild-type protein deposition." (PMID 32456156, 2020). "In Igλ-related amyloidosis (ALλ and AHL (IgGλ/IgAλ)), the SC of Igλ has not such significant superiority as Igκ in Igκ-related amyloidosis, it was even sometimes less than Igκ, FIBA or APOA1." (PMID 35418036, 2022).
Sepsis (71 papers, 2010 to 2025). Sepsis is defined as life-threatening organ dysfunction caused by a dysregulated host response to infection. "Increasing ApoA-1 levels was associated with a diminished risk of sepsis (under 75) (OR 0.927, 95% CI 0.861–0.999; p = 0.047)." (PMID 40934270, 2025). "Decreased serum apolipoprotein A1 (Apo-A1) concentration is associated with mortality in human sepsis." (PMID 32478112, 2020). "Low levels of APOA1 have been associated with poor prognosis in infective endocarditis and are independently related to 30-day mortality in sepsis." (PMID 31964768, 2020). "Human translational studies have suggested a correlation between the APOA1 gene and the risk of sepsis-associated ALI." (PMID 27708582, 2016). "The rs11216153 SNP in the APOA1 gene has also been associated with ALI risk in subjects with sepsis, with the GG genotype and G allele being more common among ALI patients than controls." (PMID 27708582, 2016). "Only the MELD prognostic index was associated with sepsis, as well as a dramatic decrease in apoA1 as previously observed." (PMID 26252713, 2015). "Three polymorphisms of the ApoA1 gene (rs11216153, rs2070665, and rs632153) were genotyped by TaqMan method in 290 patients with sepsis-associated ALI, 285 patients sepsis alone and 330 age- and sex-matched healthy controls." (PMID 24885977, 2014). "ApoA1 knockout mice have a higher risk of death from sepsis." (PMID 33195328, 2020). "In a multivariable MR analysis incorporating ApoA-1 and HDL-C, increasing ApoA-I was associated with reduced risk of sepsis (OR 0.778, 95% CI 0.611–0.990; P = 0.04), which is consistent with the results of univariable MR." (PMID 40934270, 2025). "A recent study found ApoA-1 as a useful biomarker of sepsis severity in dogs with decrease in septic shock and multiorgan dysfunction syndrome." (PMID 41437958, 2025). "In summary, a potential causal association was observed between elevated concentrations of ApoA-1, HDL, and TC and a diminished susceptibility to sepsis." (PMID 40934270, 2025). "To further investigate the translational potential of CETP inhibition, we tested the effect of acute CETPi treatment administered after the onset of S. pneumoniae–induced sepsis in female APOA1.CETP mice." (PMID 38646937, 2024). "Sepsis often leads to reduced levels of HDL-C and its associated apolipoproteins, ApoA1, and apolipoprotein C1 (ApoC1)." (PMID 39057711, 2024). "A nanoparticle integrating a fusion protein of apolipoprotein A1 and interleukin-4 and that targets myeloid-cell-rich haematopoietic organs resolves immunoparalysis in ex vivo and in vivo models of sepsis." (PMID 37291433, 2023). "In preclinical studies, infusion with reconstituted HDL or apolipoprotein A1 improved organ function and survival in rodent models of sepsis and endotoxemia." (PMID 38015312, 2023). "APOA1 was also found down-regulated in the serum of pigs with sepsis induced by LPS injection, and its reduction in serum was documented after an experimental infection by S. suis." (PMID 36430174, 2022). "TC, VLDL, and apoA-1 concentrations are significantly increased from day 1 to day 7 in pediatric patients with sepsis." (PMID 34087197, 2021). "Both apoA-1 (r = −0.55; p < 0.001) and HDL-C (r = −0.45; p < 0.001) levels were negatively related to SOFA scores, a common diagnostic tool for identifying sepsis severity." (PMID 33344516, 2020). "Similar to the reduced level of ApoA1 and A2 reported in sepsis, plasma levels of ApoC2, C3, and ApoD decreased with increasing NEC severity." (PMID 33133078, 2020). "Some studies clearly report that low HDL-C and ApoA1 concentration at admission are predictive of 18-30-day mortality and good markers of sepsis severity." (PMID 32290632, 2020). "Accordingly, higher levels of serum HDL-cholesterol, reconstituted HDL infusion, and apoA1 overexpression have been shown to improve clinical outcomes of sepsis." (PMID 29899295, 2018).
Sepsis (continued). "In ongoing in vitro studies, this research group has found that ApoA1 can potently inhibit VWF self-association and consequent platelet accumulation, and has also shown that in sepsis, ApoA1 levels correlate inversely with total active VWF." (PMID 26830467, 2016). "The liver mRNA levels of apoM and apoA1 decreased strongly upon sepsis induction and after 12 hr both were almost completely lost." (PMID 26990127, 2016). "CRP and PCT was increased (p < 0.001) and TCH, HDL-C and apoA1 (p < 0.001) were decreased in the sepsis patients." (PMID 27462492, 2016). "Taken together, the findings suggest that HDL biogenesis is impaired in the setting of sepsis through a combination of mechanisms that include decreased hepatic apoA1 expression." (PMID 23145105, 2012). "The apoA1 in the group having severe sepsis minus shock differed less from the apoA1 in controls, but the difference was still significant (P = 0.0127)." (PMID 22512779, 2012). "The severe forms of sepsis, which cause septic shock, result in severely decreased plasma levels of HDL cholesterol, apoA-1, apoC1, and CETP, and these factors have been suggested to be independent predictors of survival." (PMID 22512779, 2012). "This suggestion is consistent with other findings that injection of an apolipoprotein A1 mimetic (the major protein on HDL) peptide attenuates sepsis in rats." (PMID 23145105, 2012). "CETP inhibition improves S. pneumoniae–induced sepsis mortality in APOA1.CETP mice." (PMID 38646937, 2024). "It is possible, therefore, that the differently expressed APR proteins (Hemopexin, ApoA1, and Cluster of Alpha-2-macroglobulin) found in this study might be indicators of brain damage in the sepsis model." (PMID 36600206, 2023). "In the same manner that occurred with HRG, the relation observed with the platelet degranulation pathway may suggest that APOA1 could be a potential indicator of the presence of possible complications or increased severity in sepsis." (PMID 36430174, 2022). "An increase in the expression of APOA1 (Apolipoprotein A–I) causes a decrease in the neutrophil functions, i.e., degranulation, oxidative burst, and superoxide production, whereas a decrease in APOA1 acts as a marker of liver fibrosis and improves survival in the sepsis mice model." (PMID 35681439, 2022). "The HDL-C and apoA1 levels had a tendency to be reduced in the sepsis patients." (PMID 27462492, 2016). "TCH, HDL-C and apoA1 were significantly lower in the sepsis subjects." (PMID 27462492, 2016). "TCH, HDL-C and apoA1 decreased, particularly in sepsis patients." (PMID 27462492, 2016). "For example, proteomic studies in inflammatory states, such as sepsis, have demonstrated major changes in the composition of these particles, particularly in inflammatory proteins, such as a replacement of apoA1 by serum amyloid A (SAA), which may have an impact on patient outcomes." (PMID 35994439, 2022). "We found rs11216153 polymorphism of ApoA1 was associated with ALI, the GG genotype and G allele was common in the ALI patients (76.9%, 88.1%, respectively) than both in the control subjects (55.8%, 75.8%, respectively) and in the sepsis alone patients (58.2%, 78.4%, respectively)." (PMID 24885977, 2014). "Genetically inferred elevated ApoA-1, total cholesterol, and HDL-C manifest a protective effect against sepsis." (PMID 40934270, 2025). "And apoA1–I L4, a fusion protein of apolipoprotein A1 (apoA1) and IL4, was developed to resolve sepsis-induced immune-paralysis." (PMID 39267971, 2024). "Here, we show that treatment with the CETP inhibitor (CETPi) anacetrapib reduced mortality from Streptococcus pneumoniae–induced sepsis in APOE*3-Leiden.CETP and APOA1.CETP mice." (PMID 38646937, 2024). "For instance, in mice with polymicrobial sepsis, CETP inhibition helped maintain plasma HDL-C and apoA1 levels, resulting in higher survival rates compared with the placebo." (PMID 39057711, 2024).